IL6 (interleukin 6)
Diseases named in the same sentence as IL6 in open-access papers (continued):
Sharing a sentence is not in itself a finding about the gene and the disease.
infection (continued). "Infection with the ∆stir-2 mutant increased the expression of IL-6, IL-1β, and TNF-α at 18, 24, and 48 hpi, respectively, compared with macrophages infected with the wild-type SC09 strain or the ∆stir-2 + pSTIR-2 mutant strain." (PMID 31500298, 2019). "At 12 h after the infection, interferon-gamma, interleukin-10, interleukin-17A, interleukin-1 beta, interleukin-6, and tumor necrosis factor alpha (TNF-α) tended to be suppressed with micafungin treatment in both PF and control mouse models." (PMID 31249356, 2019). "We detected cytokine responses to a bolus of toxin and to infection; IL-6, IFN-γ, KC, and MCP-1 were the most consistent markers of inflammation." (PMID 31597722, 2019). "Interleukin 6 plays an important role in host defense against environmental stress such as infection and injury." (PMID 31523783, 2019). "A series of studies reported the upregulation of proinflammatory cytokines, such as IL-1β, IL-6, IL-12, IL-8, and IL-18, in vvIBDV infection both in vitro and in vivo." (PMID 31632367, 2019). "In agreement with previous studies, we observed induction of Groα, IL-1α, IL-8, and IL-6 following infection of HeLa cells with serovar L2." (PMID 32039039, 2019). "In response to infection or an inflammatory challenge, IL-6 production is rapidly increased by stromal cells." (PMID 31156640, 2019). "Robust production of cytokines IL-6 and IL-8 correlate with infection lethality, and clearance of the bacteria is typically mediated by PRR engagement." (PMID 31681283, 2019). "This response was marked by an enhancement in the MCP-1, GM-CSF, VEGF, RANTES and IL-17 levels and a decrease in the IL-6, a biomarker related to the severity of the infection." (PMID 31484389, 2019). "Interleukin 6 is secreted by T cells and macrophages to stimulate immune response during infection or trauma, especially burns or other tissue damage leading to inflammation." (PMID 31225686, 2019). "In our studies, we didn't establish if IL-6 has a similar effect on secondary infection with these bacteria or other S. pneumoniae serotypes." (PMID 32038632, 2019). "During infection, host innate immune cells release cytokines (primarily IL-1, IL-6 and TNFα) which act on the hypothalamus in the brain and induces a fever response." (PMID 31358780, 2019). "As with epithelial cells, infection of EVOCs with E. coli (MS499) significantly increased the secretion of IL-6 in primary epithelial cell cultures." (PMID 30923927, 2019). "In TLR7-mediated neural apoptosis upon EV71-infection, the level of IL-6 was predominantly induced in the cerebral cortex on days 3 and 5 after EV71 infection, and was also specifically modulated by TLR7." (PMID 31730654, 2019). "When the siRNAs HRSV-F, TRIM25/HRSV-F, or the combination of TRIM25 plus HRSV-F were transfected before infection, the levels of IL6, CCL5, and IFN-β mRNAs increased significantly at 24 hpi." (PMID 31035368, 2019). "Inflammation is normally induced during infection or tissue injury and can be tracked by increased levels of proinflammatory factors such as cytokines (IL6, IL8, IL18, and TNFa) in plasma samples." (PMID 31635416, 2019). "The results showed that infection of macrophages with the ∆stir-2 mutant increased the expression of IL-6, IL-1β, and TNF-α at 18, 24, and 48 hpi compared with macrophages infected with the wild-type SC09 strain or the ∆stir-2 + pSTIR-2 mutant strain." (PMID 31500298, 2019). "While in the semen, patients infected with ZIKV had higher concentrations of IL-6 and IL-10 than the control, in order to evidence the persistent inflammation since the beginning of the infection." (PMID 31828175, 2019). "Our recently published research on the characterization of vesicular stomatitis virus (VSV) pathogenesis in swine, identified a systemic upregulation of interleukin 6 (IL-6) during the acute phase of infection." (PMID 31134045, 2019). "The IL-6 can be secreted in many cell types upon appropriate stimulation during infection, inflammation or cancer." (PMID 32038632, 2019).
infection (continued). "Our current study echoes this point as the greater weight loss in WT mice corresponded to higher levels of pro-inflammatory cytokines, namely IL-6 and IFNγ at day 7 post-infection." (PMID 31539400, 2019). "The results suggest that the IL-6 abs have a neutralizing effect and indicate the persistence of the IL-6 abs even beyond acute phase of the infection." (PMID 31781117, 2019). "Noteworthy, A/J C5−/− mice have higher levels of TNF-α, IL-6, and IL-10 in the kidney when compared to A/J C5+/+ mice on the third day of infection." (PMID 31687410, 2019). "In contrast to infection of epithelial cells, infection of PMA-stimulated THP-1 cells resulted in increased production of CXCL1/Gro α, IL-1α, and IL-8 at 24 h post-infection while IL-6 was repressed by all serovars at this timepoint." (PMID 32039039, 2019). "In contrast, the Phlpp1-/- mice had 2-fold lower IL-6 levels at 5 hr post-infection, but these levels were sustained for up to 24 hr, suggestive of improper resolution of inflammation." (PMID 31408005, 2019). "In general, both the pro-inflammatory cytokines (TNF-α and MCP1) and the anti-inflammatory cytokines IL-6 and IL-10 increased 1 hour of infection in the XID infect APerC." (PMID 31536488, 2019). "Previous studies have indicated that IFN-α and IL-6 were upregulated after infection with H11N9 LPAI virus in duck peripheral blood mononuclear cells (PBMCs)." (PMID 31428075, 2019). "IL6 is involved in inflammation and infection responses, but a role of IL6 in the control of lipid metabolism has also been confirmed in several observations." (PMID 31295854, 2019). "To verify these findings, we investigated the kinetics of IL-6 and IL-8 secretion upon infection of HUVECs with A. baumannii." (PMID 31874074, 2019). "In the CNS of Ifnar1−/− mice, IFN-α1, IFN-β, TNF, IL-1α, IL-1β, and IL-6 mRNA levels were increased at day 4 post infection when compared with sham-injected controls." (PMID 31511023, 2019). "A more severe pro-inflammatory response in secondary infection group presented as higher levels of IL-6 and IL-8, was also observed in this study." (PMID 31627725, 2019). "Again at 48 h post-infection, significantly lower levels of IL-1Ra, IL-6, IL-8, IL-10, IL-12p40, GM-CSF, TNF-α, VEGF, MCP-1, and MIP-1b were observed in the ESRD group." (PMID 31875015, 2019). "The findings of a significant reduction of CCL2 and IL-6 in Myd88−/− mice in response to NMII infection are consistent with the observed reduction in leukocyte infiltration and granuloma response." (PMID 30800124, 2019). "The proinflammatory cytokines TNF-α, IFN-γ, IL-1β, IL-2, IL-5, and IL-6 also showed high levels of expression during the infection period, suggesting that the balance between cytokines determines the course of infection." (PMID 31636507, 2019). "Dam 3 exhibited an increase above baseline in IL-2, IL-6, IL-7, and IL-15; notably, all cytokines increased on day 7 and returned to basal by day 14 post-infection." (PMID 30657788, 2019). "Proinflammatory IL-1 (IL-1α and IL-β), IL-6, and IL-8 are cytokines released from macrophages in response to infection, including that with HIV and M. tuberculosis." (PMID 31341073, 2019). "IL-1β and IL-6 demonstrated variable regulation after infection with live compared to heat-inactivated V. cholerae." (PMID 31434744, 2019). "The expression of pro-inflammatory cytokines (IL-6 and IL-8) was up-regulated in epithelial cells infected with RVs, and infection of HT-29 cells with RVs increased the IL-8 level, which is dependent on protein kinase activity and NF-κB activation." (PMID 31333667, 2019). "The pro-inflammatory cytokines interleukin (IL)-1β and IL-6 levels in mouse blood plasma were significantly elevated upon infection of the wild type (PBS + DMSO vs. WT + DMSO)." (PMID 30867441, 2019).
infection (continued). "Among the tested proinflammatory and anti-inflammatory cytokines, there were significant differences in the mRNA expression levels of IL-2, IL-4, IL-6, and IL-10 following infection with the virulent vs. the attenuated strain (p < 0.05)." (PMID 31514454, 2019). "qPCR analysis indicated that knockdown of UL42 promoted HCMV- but not HSV-1-induced transcription of IFNB1, ISG56, ISG54, CXCL10, and IL6 genes at 6, 12, and 24 hr post-infection in HFFs." (PMID 31107917, 2019). "Of the remaining 2 patients with grade 4–5 infection, only one IL-6 peak appeared when grade 4–5 infection and CRS occurred at the same time." (PMID 31640816, 2019). "A rise in IL-6 has also been observed at the onset of infection in PMNd-Br mice, including the Genista strain." (PMID 30804100, 2019). "An example is a bedside interleukin-6 test for the early detection of infection in expectant mothers, to prevent pre-term births." (PMID 31802241, 2019). "In this cohort, IL-6, Acetate/Glutamate ratio and RANTES were associated with delivery within 14 days of sampling, consistent with their roles in modulating infection-inflammation-associated preterm labour in women presenting with symptoms of preterm birth." (PMID 31513646, 2019). "Of interest was the noted increase in both Iba1 and IL-6 in the frontal cortex of the day 14 post-infection fetus (compared to the control fetus and Fetus 1) despite not detecting ZIKV in the cortex of this fetus." (PMID 30657788, 2019). "Our group has recently established that in vitro infection of macrophages with MAP caused more production of pro-inflammatory cytokines such as TNFα, IL-6, and IL-12." (PMID 31817071, 2019). "Infected MAC-T cells secreted IL-6 and IL-8 over 24 hours of infection to different extents depending on the infecting strain, in agreement with the differential gene expression of IL-6 that we observed." (PMID 30992458, 2019). "It is known that the proinflammatory cytokine response (such as TNF-α and IL6 production) against any infection has several drawbacks in the host, such as pathological damage to tissues." (PMID 31089478, 2019). "In contrast to TNF, mast cells have been shown to contribute to increased IL-6 levels at the infection site (peritoneum) at very early stages following CLP." (PMID 31212724, 2019). "IL6 exerts pleiotropic actions in the organism; among them is the induction of symptoms that accompany infection, such as increased temperature." (PMID 31780867, 2019). "During infection, IL-6 and TGF-β control the relative levels of expression of the transcription factor FoxP3." (PMID 31888124, 2019). "TNF-α, IL-1β, and IL-6, 3 important pro-inflammatory cytokines, are widely accepted as downstream factors subsequent to pathogen infection and demonstrated a similar pattern." (PMID 31447841, 2019). "Whatever the bacterial lifestyle, i.e., planktonic, sessile or biofilm-dispersed, K. pneumoniae induced production of the pro-inflammatory cytokines IL-6, IL-1β, and KC in the lungs as early as 6 h post-infection." (PMID 31583108, 2019). "In the present study, we report the development and preliminary trial of a proof-of-concept version of a novel bedside test for the detection of IL-6 in biological samples from patients with brain injury or infection." (PMID 31802241, 2019). "Dynamic observation of serum IL-6 and ferritin revealed two patterns in patients with grade 4–5 infection." (PMID 31640816, 2019). "In adults, iron overload is associated with increases in complement C3 and C-reactive protein (CRP), an acute phase reactant in inflammation and infection and regulated by IL-6." (PMID 30836628, 2019). "Others have shown that TLR8 also contributes in IL-6 production during infection with Streptococcus pyogenes (group A streptococcus, GAS) and Escherichia coli in human myeloid cells." (PMID 31214180, 2019).
infection (continued). "Interferon-gamma (IFN-γ), tumor necrosis factor-alpha (TNF-α), and interleukins (e.g., IL-6, IL-10) are cell-signaling cytokines that activate and drive differentiation of immune cells upon infection." (PMID 31394828, 2019). "Both TNFα and IL-6 mRNA were markedly upregulated upon AB14 (H5N1) infection and remained at these elevated levels." (PMID 30813415, 2019). "This expression pattern contrasts that of the related cytokine IL-6, which was lowly expressed at baseline, and robustly increased during infection, before returning to baseline by 48h." (PMID 31415618, 2019). "CX3CR1 and interleukin-6 (IL-6) are both involved in inducing inflammation in response to infection and tissue injuries, while IL-6 is also involved in native T-cell differentiation." (PMID 31608121, 2019). "Significantly increased production of TNF-α, IL-6, and IL-1β was detected after infection with the wild-type strain compared to that with the ΔbceR strain." (PMID 30728810, 2019). "IL6 is known to be one of the major pro-inflammatory cytokines and participate in the infection process of bacterial pathogens." (PMID 31731575, 2019). "IL-6 is known as an inflammatory cytokine which plays an essential role on inflammation and infection responses." (PMID 30991705, 2019). "All this data from RCTs and cohort studies highlights the need for careful patient selection when treating with anti-IL-6 agents (i.e., exclusion of individuals with previous diverticulitis, exclusion of infections such as tuberculosis, fungal, etc.)." (PMID 31523783, 2019). "Interleukin 6 is a multifunctional cytokine having a role not only in inflammation and infection response, but also in regulation of metabolic, neural and reproductive processes." (PMID 31887207, 2019). "The gene expression levels of Tnfa and Il12b and the protein levels of IL-6 in the livers of μMT mice 6 weeks after infection were significantly higher than those in WT mice." (PMID 31194740, 2019). "Since IL-6, IL-10, and IL-12 cytokines were considerably elevated in PMNd-Br mice at later stages of acute infection (day 14 of infection; day 9 postdepletion), we explored the effects of anti-Brucella antibodies at these times in PMNd-Br mice." (PMID 30804100, 2019). "The results showed that the lung tissues of LL37+/+ mice released less TNF-α and IL-6 than did those of wild-type mice after 2 days of infection." (PMID 30842778, 2019). "Many studies demonstrated the important protective role of IFN-γ, nitrite, IL-17A, MIF, TNF and IL-6 during infection by T. gondii." (PMID 30809216, 2019). "IL-6 is a proinflammatory cytokine and is a key factor in host defense against environmental stress such as inflammation, infection, and injury." (PMID 31871502, 2019). "IL-6, mainly produced by alveolar epithelial cells, regulates the immune response, participates in inflammatory reactions and anti-infection defense, and is one of the main indicators of early inflammation." (PMID 31842843, 2019). "It was shown that upon infection, placentas react with an increased secretion of inflammatory molecules such as IL-6 for pathogen clearance." (PMID 31249364, 2019). "The inflammatory biomarker, IL-6 was measured in the blood samples as well, but was found to be unaffected during the course of infection which is, however, in accordance with earlier reports from humans." (PMID 31824442, 2019). "IL-6 was found to be increased by 17 times at the same point in the course of infection and 9 times at day 35 and day 42 after infection when compared to infected B6.WT mice." (PMID 29403488, 2018). "Interleukin-6 (IL-6) is one of the proinflammatory cytokines that can be detected in serum in the early stages of infection." (PMID 29675434, 2018). "IL-6 can be produced by T cells and macrophages that gives rise to immune response during infection or after injury which induces inflammation in the gastric mucosa or other tissues." (PMID 30382864, 2018).
infection (continued). "In sera, only the peak concentrations of Cxcl1 (8 h), Ccl2 (8 h), Ccl3 (8 h), IL-1β (4 h), and IL-6 (4–8 h after infection) were significantly elevated in ExoY-infected mice as compared to ExoYK81M-infected mice." (PMID 29734720, 2018). "Another study showed that inducible IL-6 and IL-8 production from HEp-2 cells upon infection with GAS strain M29588 was blocked by NF-κB and MAPK inhibitors." (PMID 29868516, 2018). "The main results of our study show that in PCa cells expressing functional JAK1, IL-6 restricts the infection of specific viruses via induction of a cell autonomous antiviral state and/or sensitization to cell death upon infection." (PMID 29441069, 2018). "Meanwhile, the expression of NOD2, as well as inflammatory factors IL-1β, TNF-α, and IL-6 was markedly up-regulated in 24 h and 48 h after infection groups." (PMID 30186539, 2018). "As expected, infection of BMDMs cells with Hh induced a sustained release of IL-6 and TNFα in the supernatants as compared to unstimulated BMDM." (PMID 29636751, 2018). "In this study we observed a significant increase in the concentration of all three inflammatory cytokines (TNF-α, IFN-γ, IL-6) in the supernatants of PBMCs infected with Mtb H37Ra compared to uninfected PBMCs at 3 days post-infection." (PMID 30204787, 2018). "Macrophages sense B. abortus and induce upregulation of IL-12, IL-1β, TNF-α, and IL-6 genes as early as 30 min after infection." (PMID 29942317, 2018). "The infection of WT mice with C. rodentium led to an increased production of the innate cytokines IL-6, TNF-α, and CSF3 (also known as G-CSF), as well as the prototype Th1 cytokine IFN-γ, and the Th17 cytokine IL-17." (PMID 29922289, 2018). "Bronchial epithelial cells carrying rs35699176 responded with a stronger inflammatory IL-6 and IL-10 response to A. fumigatus conidia after infection." (PMID 30237437, 2018). "More interestingly, while EC+ co-cultures generally had more IL-6 than EC- ones (corresponding to infection rates), LEC- co-cultures had more IL-6 than LEC+ co-cultures." (PMID 30285810, 2018). "The iron regulatory hormone hepcidin is also an acute-phase response gene that is up-regulated rapidly in infection by the action of inflammatory cytokines particularly IL-6; chronic inflammation maintains hepcidin at a high level." (PMID 29324800, 2018). "In a rhesus monkey GBS infection model, increased amniotic fluid TNF-α, IL-1β, and IL-6 occurred before uterine contractility or any clinical signs of infection, suggesting a direct role for infection in triggering preterm labor." (PMID 29520354, 2018). "Both KC and IL-6 mRNA levels were significantly elevated (>3-fold) in macrophages from control B6 mice after treatment with a TLR3 ligand poly I:C or infection with TMEV." (PMID 29410948, 2018). "Synthesized in hepatocytes by interleukin-6 (IL-6) and lipopolysaccharides (LPS), it constitutes a part of the body defence system during an infection, ensuring that iron stores are kept out of reach of the microbes." (PMID 30057485, 2018). "Again, our results demonstrated an upregulation of Th1 (IFN-γ, TNF, and IL-6) cytokines due to infection, significantly for IFN-γ in both MIF-/- and WT groups, regardless of pregnancy (P < 0.05)." (PMID 29867817, 2018). "In supernatants of DCs from mice immunized with NP30 4 and 7 weeks post‐infection, a significantly higher level of IL‐6 was observed compared to the control groups." (PMID 29577333, 2018). "In spite of the IL-6-induced reductions in productive EHDV-TAU infection of LNCaP-JAK1 cells, visual inspection of these infected cultures suggested massive cell death." (PMID 29441069, 2018). "To test if higher concentrations of IL-6 reduce EHDV-TAU infection and NS3 expression in parental LNCaP cells, we infected these cells in the presence of IL-6 (20 or 50 ng/mL)." (PMID 29441069, 2018).